CXCL14 (C-X-C motif chemokine ligand 14)
Diseases named in the same sentence as CXCL14 in open-access papers (continued):
Sharing a sentence is not in itself a finding about the gene and the disease.
Breast Tumor (3 papers, 2014 to 2023). "While CXCL14-mediated tumor suppression and altered expression correlates with better patient survival in cancer such as head and neck, colorectal, and liver, CXCL14-mediated tumor promotion mostly occurs in tumors of the breast and pancreas." (PMID 37848726, 2023). "Down-regulation of CXCL14 and TNFAIP3 has been described in various primary tumor entities including breast tumors, but to our knowledge, their role in metastasis has not been reported." (PMID 24833255, 2014).
clear cell renal cell carcinoma (3 papers, 2015 to 2019). "Together, these results suggest that elevated S100A6 enhances tumorigensis and suppresses CXCL14-induced cell apoptosis in clear cell renal cell carcinoma." (PMID 25760073, 2015). "In clear cell renal cell carcinoma, S100A6 (Calcyclin), as an oncogenic protein, negatively regulates CXCL14 expression, and knockdown of S100A6 promotes CXCL14-mediated apoptosis and promotes tumour progression." (PMID 26733763, 2016).
COVID-19 (3 papers, 2021 to 2024). A disease caused by infection with severe acute respiratory syndrome coronavirus 2. "CXCL-14 potently inhibits epithelial cell chemotaxis, and is downregulated in COVID-19 allowing sustained and enhanced immune cell recruitment." (PMID 34485339, 2021). "Conversely, CXCL-14 potently inhibits epithelial cell chemotaxis, and is downregulated in COVID-19 allowing sustained and enhanced immune cell recruitment." (PMID 34485339, 2021). "In urine, CXCL14 was significantly correlated with lymphocyte counts in COVID-19 patients, which may be used to indicate the severity of COVID-19." (PMID 36203586, 2022). "This intracellular inflammatory upregulation, combined with a downregulation of cytokine-release checkpoints (CXCL-14) contributes to the “Cytokine Release Syndrome” which is now well-described in COVID-19, and likely highly pathological." (PMID 34485339, 2021).
endometrial cancer (3 papers, 2023 to 2025). Primary or metastatic malignant neoplasm involving the endometrium (mucous membrane that lines the endometrial cavity). "CXCR4, a commonly reported receptor for CXCL14, has been implicated in the regulation of tumor metastasis in renal cell carcinoma and endometrial cancer." (PMID 40898244, 2025).
injury (3 papers, 2017 to 2020). Damage inflicted on the body as the direct or indirect result of an external force, with or without disruption of structural continuity. "Li et al38 demonstrated that antibody-mediated neutralization of Cxcl14 protects the liver from CCl4-induced acute liver injury." (PMID 28775895, 2017).
lymphoma (3 papers, 2022 to 2024). A malignant (clonal) proliferation of B- lymphocytes or T- lymphocytes which involves the lymph nodes, bone marrow and/or extranodal sites. "In Compagno Lymphoma Statistics26, CXCL14 was overexpressed in DLBCL versus normal tissue with a fold change of 5.168." (PMID 35181719, 2022). "Among these genes, CXCL14 has the largest number of nodes and its function on lymphoma has not been reported yet." (PMID 35452413, 2022).
oral cancers (3 papers, 2016 to 2021). "CXCL14 expression is frequently downregulated in cervical, prostate, colorectal, lung, and oral cancers (13, –, 16, 18, 36, 37)." (PMID 27143385, 2016). "While normal human epithelial cells constitutively express CXCL14, its expression is frequently reduced in cervical, prostate, and oral cancers (13, –, 15)." (PMID 27143385, 2016). "In addition, CXCL14 correlates with poor patient outcome in oral cancers and has significant effects on the tumorigenesis and proliferation of oral cancers by mediating DNA methylation and leukocyte migration." (PMID 34696665, 2021).
oropharyngeal carcinoma (3 papers, 2016 to 2023). Carcinoma, predominantly squamous cell, arising from the epithelial cells of the oropharynx. "Using in vivo mouse models, we revealed that restoration of Cxcl14 expression in HPV-positive mouse oropharyngeal carcinoma cells clears tumors in immunocompetent syngeneic mice, but not in Rag1-deficient mice." (PMID 27143385, 2016).
papillary thyroid carcinoma (3 papers, 2013 to 2023). "Additionally, CXCL14 have been suggested to be a poor prognostic marker in papillary thyroid carcinoma by qPCR analysis." (PMID 23294544, 2013). "As it has been noted on previous work: CST6, CXCL14, DHRS3, and SPP1 are regulated by BRAF signaling and may play a role in papillary thyroid carcinoma pathogenesis." (PMID 25887408, 2015). "It has also been documented that CXCL14 transcript is markedly higher in papillary thyroid carcinoma than in adjacent noncancerous tissues and positively correlated with lymph node metastasis." (PMID 23294544, 2013).
prostate tumor (3 papers, 2009 to 2019). "Prostate tumors develop rapidly and display increased angiogenesis in the presence of CXCL14 overexpressing cancer associated fibroblasts." (PMID 29507348, 2018). "Both SFRP4 and CXCL14 on the other hand are inhibitors of prostate tumor growth." (PMID 19356222, 2009).
tongue cancer (3 papers, 2012 to 2019). A malignant neoplasm affecting the tongue. "Consistently, CXCL14 downregulation suppresses migration of colorectal and tongue cancer cell lines." (PMID 27143385, 2016). "The forced expression of CXCL14/BRAK in tongue carcinoma cells decreases the rate of tumor formation and size of tumor xenografts in athymic nude mice and SCID mice." (PMID 23762619, 2012). "Moreover, CXCL14 expression was reduced in tongue carcinoma tissue compared with that in surrounding normal tissues, indicating that CXCL14 exhibits tumor-suppressive activity toward HNSCC in vivo." (PMID 31014014, 2019).
triple-negative breast carcinoma (3 papers, 2018 to 2025). An invasive breast carcinoma which is negative for expression of estrogen receptor (ER), progesterone receptor (PR), and human epidermal growth factor receptor 2 (HER2). "Importantly, low CXCL14 expression levels have been specifically associated with poor survival rates in triple-negative breast cancer patients." (PMID 41139924, 2025).
acute coronary syndrome (2 papers, 2021 to 2023). Signs and symptoms related to acute ischemia of the myocardium secondary to coronary artery disease. "Baseline platelet-associated but not circulating CXCL14 levels were significantly lower in patients with chronic coronary syndrome (mean fluorescence intensity logarithmized, 1.35 ± 0.35) when compared to those with acute coronary syndrome (1.47 ± 0.38) and without CAD (1.51 ± 0.40)." (PMID 37255851, 2023).
acute kidney injury (2 papers, 2020 to 2022). Sudden and sustained deterioration of the kidney function characterized by decreased glomerular filtration rate, increased serum creatinine or oliguria. "Other studies have identified the role of CXCL14 in the innate immune response from its inhibition of proinflammatory cytokines in acute kidney injury and the regulation of T cells in stroke, indicating a pivotal role of CXCL14 as an anti-inflammatory and immune mediator." (PMID 36012586, 2022).
asthma (2 papers, 2017 to 2025). "Exploring the role and mechanism of CXCL14 in DCs phenotype remodeling and bronchial asthma will contribute to a better understanding of asthma pathogenesis and provide essential targets for its prevention and treatment." (PMID 41036310, 2025). "Western blot and qRT‐PCR analyses demonstrated that CXCL14 expression was significantly higher in the lung tissues of asthma mice compared to the control group." (PMID 41036310, 2025). "Immunohistochemistry results (***P < 0.001) further showed a pronounced increase in CXCL14 expression in the asthma group." (PMID 41036310, 2025). "This study found that CXCL14 promotes the maturation and activity of DCs, and knocking down CXCL14 can suppress excessive immune responses under certain conditions, which is crucial for balancing the immune response in asthma." (PMID 41036310, 2025). "Inhibiting CXCL14 production may help suppress excessive airway remodeling and chronic inflammation in asthma patients, thereby slowing disease progression." (PMID 41036310, 2025). "In this study, to understand the correlation between C‐X‐C motif chemokine ligand 14 (CXCL14) in bone marrow dendritic cells (BMDCs) and antigen presentation of asthma dendritic cells (DCs), an in vitro model of BMDCs was constructed for RNA sequencing (RNA‐seq)." (PMID 41036310, 2025). "Moreover, CXCL14 regulates local immune responses in the airways during asthma by affecting DC maturation and activation." (PMID 41036310, 2025). "Therefore, CXCL14 may play an important role in both acute exacerbations and the maintenance of chronic airway inflammation in asthma." (PMID 41036310, 2025). "Following CXCL14 knockdown, both the total cells in BALF (**P < 0.01) and the absolute eosinophils count (**P < 0.01) were reduced compared to the AAV‐GFP group in asthma mice." (PMID 41036310, 2025).
Autoimmunity (2 papers, 2017 to 2025). The occurrence of an immune reaction against the organism's own cells or tissues. "Spatially, PNPs—particularly those mediated by autoimmunity—exhibited focal perineurial hyperplasia and increased expression of CXCL14, identified as perineurial cell marker." (PMID 40849297, 2025).
basal cell carcinoma (2 papers, 2017 to 2019). A carcinoma involving the basal cells. "Moreover, a study-using laser capture microdissection revealed CXCL12 and CXCL14 to be upregulated in stroma of prostate and basal cell carcinomas." (PMID 28178651, 2017).
colorectal tumor (2 papers, 2013 to 2021). "In this study, we found that CXCL14 was frequently up-regulated in colorectal tumors compared with the adjacent normal colorectal mucosa." (PMID 23294544, 2013). "CXCL14 expression was markedly up-regulated in colorectal tumor tissues compared with normal colorectal mucosa (P < 0.001)." (PMID 23294544, 2013).
diabetes (2 papers, 2023). "CXCL14 may recruit macrophages into adipose tissue to produce large amounts of cytokines, chemokines, and growth factors to induce chronic inflammation, thereby promoting the progression of obesity-related diseases such as diabetes and cancer." (PMID 37835681, 2023).
ductal carcinoma in situ (2 papers, 2013 to 2019). "Intriguingly, CXCL14 expression was observed to be restricted to the myoepithelial cells in ductal carcinoma in situ and the tumor epithelial cells in invasive breast carcinoma, suggesting CXCL14 might be converted into an autocrine factor from a paracrine factor." (PMID 23294544, 2013).
endometrioid ovarian cancer (2 papers, 2022 to 2024).
endometriosis (2 papers, 2022 to 2024). The growth of functional endometrial tissue in anatomic sites outside the uterine body. "We identified that genes involved in immune surveillance, such as TIMP3 and CXCL14 were increased in the decidualizing stromal cells from donors with endometriosis relative to cells from normal donors." (PMID 38402336, 2024).
Hepatic steatosis (2 papers, 2013 to 2015). Steatosis is a term used to denote lipid accumulation within hepatocytes. "Expression levels of C-C chemokine receptor 1 (CCR1) and chemokine (C-X-C motif) ligands 9, 10, 14 (CXCL9, CXCL10, and CXCL14) are increased in livers during HFD-induced hepatic steatosis." (PMID 25887406, 2015).
Hepatitis (2 papers, 2008 to 2021). Inflammation of the liver. "Proteins that uniquely distinguish HCC patients with low AFP from patients with hepatitis include IL1RN, IFNG, CDKN1A, RETN, CXCL14, and FGF2." (PMID 19578489, 2008). "Importantly, we also identified 8 proteins that significantly differentiate HCC patients with ‘normal’ levels of AFP (< 20 ng/ml) from hepatitis patients (p < 0.05) (IL1RN, IFNG, CDKN1A, RETN, CXCL14, CTNNB, FGF2, and SELL)." (PMID 19578489, 2008).
lung disease (2 papers, 2020 to 2024). "The effect of CXCL14 on fibroblasts is noteworthy, as CXCL14 induced a fibrosis gene expression profile, linking this chemokine with lung disease, whereas stimulation of tumor-associated fibroblasts with CXCL14 led to the generation of tumor-promoting factors." (PMID 33123134, 2020). "However, CXCL14 levels can be massively upregulated in lung disorders, both on the mRNA and the protein level." (PMID 38184723, 2024).
mesenchymal tumors (2 papers, 2019 to 2021). "CXCL14 enhances the sphere-forming ability of GBM cells, overexpresses in mesenchymal tumors and is responsible for tumor onset, growth and recurrence." (PMID 33816228, 2021).
metastatic disease (2 papers, 2022 to 2024). "Even if therapeutic levels of CXCL14 could be clinically attained, the local application of CXCL14 to (or from) a single tumor site may not instigate an adequate immune response to promote cancer clearance in patients with advanced metastatic disease." (PMID 38400076, 2024).
myocardial infarction (2 papers, 2023 to 2024). Gross necrosis of the myocardium, as a result of interruption of the blood supply to the area, as in coronary thrombosis. "CXCL14 is a target of miR-1278, which exerts a protective role in cardiac tissue against myocardial infarction." (PMID 38461325, 2024). "CXCL14 has also been shown to be inhibited by miR-1278 in tissue subject of myocardial infarction in mouse model." (PMID 38461325, 2024).
nasopharyngeal carcinoma (2 papers, 2024 to 2025). A carcinoma arising from the nasopharyngeal epithelium. "In nasopharyngeal cancer survivors, elevated FGF2 levels in tissues activate CXCL14, promoting M2 macrophage polarization and tumor metastasis." (PMID 39436561, 2024).
neuroblastoma (2 papers, 2024 to 2025). Neuroblastoma (NB) is the most common solid, extracranial childhood tumor. "In preliminary experiments, it was identified that HK3 in neuroblastoma regulates the polarization and recruitment of M2-like macrophages through the secretion of CXCL14." (PMID 38714539, 2024). "This suggests that the expression of CXCL14 in neuroblastoma is also regulated by the PI3K-AKT signaling pathway." (PMID 38714539, 2024). "ELISA also confirmed lower protein secretion of CXCL14 in the two HK3-knockout neuroblastoma cell lines." (PMID 38714539, 2024). "Consequently, HK3 modulates the interaction between neuroblastoma and M2-like macrophages by secreting CXCL14 through the PI3K/AKT signaling pathway." (PMID 38714539, 2024). "Therefore, HK3 exerts its influence on the interaction between neuroblastoma cells and M2-like macrophages by modulating CXCL14 via the PI3K-AKT signaling pathway." (PMID 38714539, 2024). "It was speculated that CXCL14 might play a role in the interaction between neuroblastoma and TAMs." (PMID 38714539, 2024). "This suggests that CXCL14 serves as a downstream molecule in neuroblastoma (NB), and HK3 regulates the recruitment and polarization of M2-like macrophages through CXCL14." (PMID 38714539, 2024). "Transcriptome sequencing and GSEA enrichment analysis revealed a significant reduction in CXCL14 expression in neuroblastoma cells with knocked-down HK3, accompanied by a notable decrease in secreted CXCL14." (PMID 38714539, 2024). "Subsequent verification demonstrated that HK3 activation in neuroblastoma triggers the PI3K-AKT signal transduction pathway, thereby influencing the expression of CXCL14 in neuroblastoma." (PMID 38714539, 2024).
osteoarthritis (2 papers, 2016 to 2024). A noninflammatory degenerative joint disease occurring chiefly in older persons, characterized by degeneration of the articular cartilage, hypertrophy of bone at the margins and changes in the synovial membrane. "In contrast, fewer CD8+ T cells producing CXCL14 and IL-32 were identified in osteoarthritis synovium." (PMID 39114979, 2024). "To demonstrate the clinical relevance of CXCL14- and IL-32–producing cells in PsA, we stained synovial tissue sections collected from patients with PsA and osteoarthritis and found IL-32+ and CXCL14+ cells in the synovial lining area and ectopic lymphoid aggregates of the patient with PsA." (PMID 39114979, 2024).
Abdominal obesity (1 paper, 2024). Excessive fat around the stomach and abdomen. "We highlight CXCL14 as a marker of aging and abdominal obesity that is positively correlated with genes associated with fibrosis and ECM remodeling." (PMID 39141531, 2024). "We highlight CXCL14 as marker of aging particularly in individuals with greater abdominal obesity (WHR) and discovered that CXCL14 strongly correlated with genes associated with fibrosis and ECM remodeling." (PMID 39141531, 2024).
allergic asthma (1 paper, 2025). A asthma with a basis in a pathological type I hypersensitivity reaction. "The expression of CXCL14 was increased in the HDM‐induced allergic asthma model." (PMID 41036310, 2025).
anaplastic large cell lymphoma (1 paper, 2022). Anaplastic large cell lymphoma (ALCL) is a rare and aggressive peripheral T-cell non-Hodgkin lymphoma, belonging to the group of CD30-positive lymphoproliferative disorders, which affects lymph nodes and extranodal sites. "Upregulated CXCL14 expression was also found in breast implant-associated anaplastic large cell lymphoma, and the over-expressed CXCL14 was associated with poor survival in non-small cell lung cancer (NSCLC) patients after curative resection." (PMID 35452413, 2022).
Anorexia (1 paper, 2010). Lack of desire to eat (loss of appetite). "This experiment was made more difficult by the fact that CXCL14−/− mice showed severe anorexia after the first ICV injection, regardless of whether PBS or CXCL14 was injected." (PMID 20428232, 2010).
astrocytoma (1 paper, 2024). "Thus, we tested CXCL14 at the mouse MRGPRB2 stably expressed in 1321N1 astrocytoma cells using calcium mobilization assays." (PMID 38184723, 2024).
atrial fibrillation (1 paper, 2011). A disorder characterized by an electrocardiographic finding of a supraventricular arrhythmia characterized by the replacement of consistent P waves by rapid oscillations or fibrillatory waves that vary in size, shape and timing and are accompanied by an irregular ventricular response. "Recently, Cxcl14, also known as Pf4 (platelet factor 4), was found to be slightly elevated in the left atrium of patients with atrial fibrillation." (PMID 22039477, 2011).
atrophic gastritis (1 paper, 2020). "In an atrophic gastritis environment, the expression of CXCL14, CCL4, CCL26, CCL21, CCL2, CCL19, and CCL13 was correlated with the infiltration of central memory CD4 T cell." (PMID 33426088, 2020). "In superficial gastritis and atrophic gastritis, the expression levels of chemokines/interleukins are relatively the same (IL14, CXCL14, and CCL28 had higher expression levels; IL3, CCL26, IL31, etc., had lower expression levels), only with a slight difference." (PMID 33426088, 2020).
autism (1 paper, 2019). Persistent deficits in social interaction and communication and interaction as well as a markedly restricted repertoire of activity and interest as well as repetitive patterns of behavior. "Other protein factors with altered expression in LPFC layer 1 in autism include chemokine ligand 14 (CXCL14) and neuron-derived neurotrophic factor (NDNF)." (PMID 30867066, 2019). "CXCL14, an inflammatory cytokine, is involved in the regulation of myelination; reduction in the expression of this cytokine results in a reduction in myelination, which is consistent with our findings of reduced myelination and increased branching in prefrontal cortices of adults with autism." (PMID 30867066, 2019).
Bovine mastitis (1 paper, 2024). INFLAMMATION of the UDDER in cows. "Similarly, CXCL14, located in a BTA7 CSS cluster region for the Blanco Orejinegro and Limonero breeds, has also been implicated in the immune response to bovine mastitis caused by Staphylococcus aureus." (PMID 38571912, 2024).